CFH (complement factor H)
Description:
Glycoprotein that plays an essential role in maintaining a well-balanced immune response by modulating complement activation. Acts as a soluble inhibitor of complement, where its binding to self markers such as glycan structures prevents complement activation and amplification on cell surfaces. Accelerates the decay of the complement alternative pathway (AP) C3 convertase C3bBb, thus preventing local formation of more C3b, the central player of the complement amplification loop. As a cofactor of the serine protease factor I, CFH also regulates proteolytic degradation of already-deposited C3b. In addition, mediates several cellular responses through interaction with specific receptors. For example, interacts with CR3/ITGAM receptor and thereby mediates the adhesion of human neutrophils to different pathogens. In turn, these pathogens are phagocytosed and destroyed. (Microbial infection) In the mosquito midgut, binds to the surface of parasite P.falciparum gametocytes and protects the parasite from alternative complement pathway-mediated elimination.
Synonyms: HF; HF1; HF2; HUS; FHL1; ARMS1; ARMD4; AHUS1; AMBP1; CFHL3; FH
Tractability: Small molecule: a structure with a bound ligand is known. Antibody: its Gene Ontology location is reachable by antibodies, with high confidence; UniProt places it where antibodies can reach, with medium confidence; UniProt predicts a signal peptide or a membrane-spanning region. PROTAC: its protein half-life has been measured.
Target class: Secreted protein
Gene: Protein-coding gene on chromosome 1 (196,651,754 to 196,752,476, forward strand). Ensembl gene ENSG00000000971.
Subcellular location: Secreted
Subcellular location (Human Protein Atlas): Vesicles; Predicted to be secreted
Pathways (Reactome):
Immune System: Regulation of Complement cascade
Gene Ontology:
Molecular function: heparan sulfate proteoglycan binding; heparin binding; identical protein binding; protein binding; complement component C3b binding
Biological process: central nervous system myelination; complement activation; complement activation, alternative pathway; inflammatory response; proteolysis; regulation of complement activation; regulation of complement activation, alternative pathway; regulation of complement-dependent cytotoxicity; cell development; neurogenesis
Cellular component: blood microparticle; extracellular exosome; serine-type endopeptidase complex; symbiont cell surface; extracellular region
Genetic constraint (gnomAD): Loss-of-function variants: 40 observed, 121.05 expected, observed/expected ratio (o/e) 0.33, 90% interval 0.26 to 0.43. The upper end of that interval is the gene's LOEUF score, 0.43, which puts it in group 1 of 6, group 1 being the genes least tolerant of losing a copy. Missense variants: 1,223 observed, 1,372.2 expected, observed/expected ratio (o/e) 0.89, 90% interval 0.85 to 0.93. Synonymous variants: 475 observed, 452.54 expected, observed/expected ratio (o/e) 1.05, 90% interval 0.97 to 1.13.
Gene-disease validity (ClinGen):
ClinGen rates the evidence that CFH causes each of these diseases.
atypical hemolytic-uremic syndrome (semidominant): Definitive. A rare, genetic thrombotic microangiopathy due to dysregulation of the alternative complement pathway and characterized by the triad of hemolytic anemia, thrombocytopenia, and acute renal dysfunction.
C3 glomerulonephritis (autosomal recessive): Definitive. Glomerulonephritis characterized by C3 accumulation with little or absent deposition of immunoglobulin, in the absence of ultrastructural electron-dense transformation seen in dense deposit disease.
Homologues: Orthologues: chimpanzee CFH (97% identical), macaque CFH (88% identical). Paralogues in human: CFHR5 (25% identical), CFHR1 (19% identical), CFHR3 (18% identical), CSMD3 (17% identical), CSMD1 (17% identical), F13B (17% identical), SVEP1 (17% identical), CFHR4 (16% identical), CSMD2 (16% identical), PAPPA2 (16% identical), PAPPA (15% identical), CFHR2 (12% identical), and 27 more.
Diseases named in the same sentence as CFH in open-access papers:
CFH is named in the same sentence as 261 diseases in open-access papers, as found by Europe PMC text mining. Sharing a sentence is not in itself a finding about the gene and the disease. The quoted sentences say what the papers report.
age-related macular degeneration (162 papers, 2006 to 2026). Age-related loss of vision in the central portion of the retina (macula), secondary to retinal degeneration. "In 2005, Klein and colleagues conducted a pioneering GWAS that identified genetic variants near the Complement Factor H (CFH) gene locus associated with age-related macular degeneration." (PMID 41366292, 2025). "Among more than 100 associated loci, the most prominent are complement factor H (CFH) and age-related maculopathy susceptibility 2/high temperature requirement A serine peptidase 1 (ARMS2/HTRA1)." (PMID 41516080, 2025). "Complement factor H (CFH) common genetic variants have been associated with age-related macular degeneration (AMD)." (PMID 39753135, 2025). "The GWA 2005 study, which examined 96 cases and 50 controls for polymorphisms associated with age-related macular degeneration, identified two variants in the Complement Factor H (CFH) locus as strongly associated with AMD: rs380390 and rs10272438." (PMID 39219434, 2025). "These include C1S, a serine protease of the classical pathway, and complement Factor H (CFH), a regulator of the alternative pathway more strongly associated with age-related macular degeneration but functionally relevant to neuroinflammation." (PMID 41398960, 2025). "Specific CFH subtypes, such as rs1061170 and rs141099, have been associated with a significantly increased risk of developing age-related macular degeneration (AMD)." (PMID 40331961, 2025). "The single nucleotide polymorphisms (SNPs) of complement factor H (CFH) gene are well-known genetic risk factors for age-related macular degeneration (AMD)." (PMID 36379987, 2022). "It has been reported that ARMS2 and CFH are two major genes susceptible to age-related macular degeneration (AMD) through genome-wide association studies." (PMID 33920794, 2021). "Genetic variants of the CFH gene, which encodes the CFH protein, are associated with age-related macular degeneration (AMD)." (PMID 32157596, 2020). "Mutations in complement-associated genes, and particularly in the CFH gene, have been shown to be associated with age-related macular degeneration (AMD), one of the leading causes of blindness worldwide." (PMID 28275964, 2018). "One gene that was of interest, based on previously published GWAS studies was serum complement factor H. Several studies have shown an association of CFH mutations with age related macular degeneration as well as with other eye diseases including uveitis." (PMID 25756647, 2015). "A common polymorphism in the complement factor H gene (rs1061170, Y402H) is associated with a high risk of age-related macular degeneration (AMD)." (PMID 23596508, 2013). "The purpose of the study was to determine serum complement factor H (CFH) levels in patients of age related macular degeneration (AMD) and examine its association with CFH Y402H polymorphism." (PMID 23922956, 2013). "The purpose of this study was to investigate the association of ARMS2/HTRA1 and CFH SNPs with early age-related maculopathy (ARM) in a Han Chinese cohort." (PMID 23687431, 2013). "Since the study that identified the association of complement factor H (CFH) with age-related macular degeneration (AMD) in 2005, over 450 GWAS have been performed and more than 2,000 susceptible SNPs or genetic loci have been reported." (PMID 21504591, 2011). "Association between the complement factor H (CFH) Y402H polymorphism (CFH 402) and age-related macular degeneration (AMD) has been shown in twelve or so different Caucasian populations." (PMID 17438519, 2007). "This was the case for a genome-wide association study of age-related macular degeneration – only 96 cases and 50 controls were sufficient to identify genome-wide association with complement factor H." (PMID 17903304, 2007). "In this study, we confirm the strong association between polymorphisms in the complement factor H gene and advanced age-related macular degeneration in 3 independent predominantly Caucasian populations." (PMID 18043728, 2007).
age-related macular degeneration (continued). "Associations between CFH (complement factor H) and age-related macular degeneration have been replicated in numerous studies." (PMID 17940599, 2007). "Odds ratios for the joint and marginal effects of single nucleotide polymorphisms complement factor H 402 and rs11200638 on age-related macular degeneration." (PMID 17438519, 2007). "In a recent small GWAS of age-related macular degeneration that included 96 cases and 50 controls, an association with the CFH gene was identified and confirmed in larger studies." (PMID 17903305, 2007). "It has been established in several independent cohorts that CFH alleles act as a susceptibility factor for age-related macular degeneration and type II membranoproliferative glomerulonephritis." (PMID 17076561, 2006). "The deficiency of CFH has been shown to be associated with a variety of diseases, such as membranoproliferative glomerulonephritis, atypical hemolytic uremic syndrome (aHUs), age-related macular degeneration (AMD), etc.." (PMID 38784225, 2024). "In age-related macular degeneration, which is also associated with AAbs against CFH, it has been reported that these AAbs tend to recognize a wide region within the N-terminal domains of CFH (CCP1-8)." (PMID 35452676, 2022). "Furthermore, CFH gene polymorphisms are also associated with multiple inflammatory diseases, such as age-related macular degeneration, diabetic retinopathy, and atypical hemolytic-uremic syndrome." (PMID 33643312, 2021). "Additionally, genetic variants of CFH are strongly associated with age-related macular degeneration (AMD), and CFH has been shown to inhibit the anti-inflammatory activity of CD47." (PMID 32157596, 2020). "However, a mutation in a gene encoding complement factor H was linked to membranoproliferative glomerulonephritis, hemolytic uremic syndrome, and age-related macular degeneration." (PMID 33383894, 2020). "The risk (major) allele (G) of the rs6677604 variant is a non-coding SNP located in intron 11 of CFH and has previously been described to increase susceptibility for age-related macular degeneration and IgA nephropathy and to decrease susceptibility for systemic lupus erythematosus." (PMID 31883521, 2019). "Recently, a number of studies have reported remarkably strong, replicable associations with complex disease, including the complement factor H (CFH) gene in age-related macular degeneration and the transcription factor 7-like-2 (TCF7L2) gene in type 2 diabetes." (PMID 18335027, 2008). "CFH accelerates the alternative C3 convertase through competitive binding with C3b and its inadequate recognition of cells can cause conditions such as atypical hemolytic uremic syndrome (aHUS), age-related macular degeneration (ARMD), and membrano-proliferative glomerulonephritis type II." (PMID 41356214, 2025). "Complement dysregulation in the eye has been implicated in the pathogenesis of age-related macular degeneration (AMD), and genetic variants of complement factor H (CFH) are strongly associated with AMD risk." (PMID 37471073, 2023). "CFH proteins have been reported to be associated with some natural diseases including age-related macular degeneration (AMD), atypical hemolytic uremic syndrome (aHUS) as well as multiple cancers." (PMID 35852862, 2022). "Numerous CFH variants are associated with age-related macular degeneration (AMD), but their functional consequences frequently remain undetermined." (PMID 36445700, 2022). "The first successful GWAS study was published in 2002 on myocardial infarction, followed by a landmark study on age-related macular degeneration (AMD) that identified the complement factor H gene as a major risk factor for AMD." (PMID 34440374, 2021). "A common allele (402H) of the complement factor H (FH) gene is the major risk factor for age-related macular degeneration (AMD), the leading cause of blindness in the elderly population." (PMID 32318056, 2020).
age-related macular degeneration (continued). "As early as 2005, single nucleotide polymorphisms (SNP) in the complement factor H (CFH) gene were identified as genetic risk factors for age-related macular degeneration (AMD), the major cause of visual impairment in the Western world." (PMID 32859013, 2020). "In recent years, multiple CFH SNPs have been investigated for association with human diseases, such as age-related macular degeneration (AMD)." (PMID 31861421, 2019). "Individuals homozygous for risk variants of CFH, when exposed to Chlamydia pneumoniae, were found to face an increased risk of age-related macular degeneration (AMD) progression." (PMID 30089174, 2018). "These different drusen phenotypes are associated with certain genotypic variants such as those in the complement factor H (CFH) and age-related maculopathy susceptibility (ARMS2) loci, and may have differential propensity for progression to RPE atrophy and late-stage AMD12,13." (PMID 29101353, 2017). "The genetic architecture of age-related macular degeneration (AMD) involves numerous genetic variants, both common and rare, in the coding region of complement factor H (CFH)." (PMID 27572114, 2016). "The complement factor H (CFH) tyrosine 402 histidine (Y402H, rs1061170) variant is known to be significantly associated with age-related macular degeneration (AMD)." (PMID 24863099, 2014). "It is a longstanding puzzle why non-coding variants in the complement factor H (CFH) gene are more strongly associated with age-related macular degeneration (AMD) than functional coding variants that directly influence the alternative complement pathway." (PMID 23873044, 2013). "Single nucleotide polymorphisms (SNPs) of age-related maculopathy susceptibility protein 2/HtrA serine peptidase 1 (ARMS2/HTRA1) and complement factor H (CFH) have been reported to be associated with age-related macular degeneration (AMD)." (PMID 23687431, 2013). "One of the early successes of GWAS was the identification of the Complement Factor H gene as a major risk factor for age-related macular degeneration or AMD." (PMID 23300413, 2012). "In genetic studies on age-related macular degeneration (AMD), its association with the CFH gene led to the discovery that other molecules in the complement pathway were also associated with the condition, such as C2/CFB, C3, and CFI." (PMID 23213273, 2012). "In our previous studies, we have found that polymorphisms in the CFH gene are associated with the development of neovascular age-related macular degeneration (AMD) as well as anterior uveitis in females." (PMID 22876110, 2012). "The Tyr402His polymorphism of complement factor H (FH) with 20 short complement regulator (SCR) domains is associated with age-related macular degeneration (AMD)." (PMID 21396937, 2011). "Complement factor H shows very strong association with Age-related Macular Degeneration (AMD), and recent data suggest that multiple causal variants are associated with disease." (PMID 22022419, 2011). "In our previous study, we found SNP rs800292 in CFH was associated with age-related macular degeneration (AMD) in Chinese patients." (PMID 22065918, 2011). "Recent genetic studies show that polymorphisms in complement factor B and H (CFH) are important for the development of age-related macular degeneration (AMD) and its vascular pathology." (PMID 21379381, 2011). "Age-related macular degeneration (ARMD) has been strongly associated with genetic variation in the gene encoding complement factor H (CFH)." (PMID 21532833, 2010). "Major genetic factors for age-related macular degeneration (AMD) have recently been identified as susceptibility risk factors, including variants in the CFH gene and the ARMS2 LOC387715/HTRA1locus." (PMID 19806217, 2009). "The Tyr402His variant of complement factor H (CFH) is associated with age-related macular degeneration (AMD) in several populations." (PMID 18852870, 2008).